SST (somatostatin)
Diseases named in the same sentence as SST in open-access papers (continued):
Sharing a sentence is not in itself a finding about the gene and the disease.
infection (24 papers, 2005 to 2025). The state of being infected such as from the introduction of a foreign agent such as serum, vaccine, antigenic substance or organism. "In a later phase of infection (6–8 months H. suis infected pigs), markers for gastric acid secretion were downregulated, genes encoding somatostatin were upregulated and the number of G-cells was decreased, indicating inhibition of gastric acid secretion." (PMID 28619040, 2017). "The increased plasma concentrations of somatostatin may be involved to counter the inflammation caused by infection." (PMID 33805275, 2021). "We used the knock-in SstCre and VipCre lines to target initial infection to either somatostatin (Sst)-expressing or vasoactive intestinal peptide (Vip)-expressing inhibitory neurons." (PMID 38096019, 2023). "Whereas PDX1 + NGN3 resulted in appearance of only somatostatin-positive cells, infection with all three PNM factors resulted in expression of somatostatin and insulin in mutually exclusive cells." (PMID 33111125, 2020). "While infection with the separate vectors induced both somatostatin- and insulin-expressing cells, infection with Ad-M3-mCherry resulted in the induction of predominantly insulin-expressing cells." (PMID 33111125, 2020). "In SST-Cre mice, we found that at 24–36 hr after infection there were a small number of GFP(+) cells in the NAc, and no GFP(+) cells in any other regions." (PMID 30845266, 2019). "Further studies, measuring the levels of IL-1β, gastrin, histamine and somatostatin after long term experimental infection, are necessary to obtain additional insights into the influence of H. heilmannii s.s. on gastric homeostasis." (PMID 23895283, 2013). "Endogenous somatostatin levels were increased at wk10 (297 ± 37.24 pg/ml) and wk14 (206 ± 13.30 pg/ml) of infection as compared to uninfected mice (119 ± 11.99 pg/ml) (P = 0.01; 0.008 respectively)." (PMID 15949036, 2005). "Progression of the infection from acute (week 10) to chronic (week 14) stages resulted in a drop in the somatostatin levels." (PMID 15949036, 2005). "Furthermore, early postoperative measures are equally critical, including ensuring adequate drainage, preventing infection, and administering somatostatin analogs to reduce pancreatic juice secretion." (PMID 41268114, 2025). "For cases of postoperative bile fistula, due to the patient's stable vital signs and no obvious signs of peritonitis, we first adopted conservative treatment including abrosia, antibiotic anti-infection, total parenteral nutrition, and somatostatin inhibition of glandular secretion." (PMID 37404555, 2023). "Selective primary infection of SST+ neurons resulted in trans-synaptic labelling of only 9+ PCs." (PMID 37468512, 2023). "The infection also decreases the expression of mucosal D cell and somatostatin production." (PMID 35453805, 2022). "We can therefore conclude that somatostatin-secreting Delta cells are one of the susceptible cell types to infection, with no information available on other cell types, given their relative low abundance in this RP-GO model." (PMID 34785679, 2021). "However, for somatostatin a significant decrease of mRNA levels was measured not only in antral, but also in corpus mucosa after 4 weeks of infection." (PMID 19270747, 2009). "Interestingly, Math6 mRNA expression declined 48 h post-infection, whereas levels of other Neurog3-induced mRNAs were maintained (Pax4, NeuroD1) or remained elevated (somatostatin) through 72 h." (PMID 18560595, 2008). "However, we cannot discount the possibility that NPFF or other Mrgpra1 ligands, like substance P and somatostatin, secreted by other cells in the pulmonary tissue, may be induced during infection to modulate neutrophil function." (PMID 38295799, 2024). "Increased plasma levels of corticosterone and somatostatin were observed in NDV-infected chicken at three- and five- days post infection (DPI)." (PMID 33805275, 2021).
infection (continued). "The analysis showed that although there are starter cells in L2-6 at both time points we get robust primary infection in L2/3 for both VIP+ and SST+ cells." (PMID 33184269, 2020). "As previously established, we euthanized 2 mice every 12 hr after infection with PRV-Introvert-GFP for 72 hr and observed GFP expression in canonical NAc afferents in SST-Cre and wild-type C57BL/6J mice." (PMID 30845266, 2019). "We fractionated cells produced by Ad-RFP-Neurog3 infection by RFP intensity and measured mRNA expression of Neurog3, CHGA, SST and GHRL by qRT-PCR." (PMID 24252877, 2013). "Immunostaining confirmed these qRT-PCR findings and demonstrated that only RFP+ cells produced by Ad-RFP-Neurog3 infection were immunostained with antibodies recognizing NEUROD1, NKX2.2, CHGA, SST or GHRL." (PMID 24252877, 2013). "Our findings are in agreement with these observations, but substantially advance those by showing that in addition to PV and SST inhibitory cells, GABAergic neurons expressing nNOS, NPY, and CCK can be also a subject of infection by CaMKIIα promoter-controlled constructs." (PMID 36963833, 2023). "Our experiments revealed that the SSTR2 expression was enhanced under these inflammatory and microbial conditions, indicating that the SST/SSTR system might play an important role in periodontal inflammation and infection." (PMID 30609928, 2019). "We found that prenatal infection reduced the density of parvalbumin- but not somatostatin-positive interneurons in the CA1 area of the hippocampus and strongly reduced the strength of inhibition early during postnatal development." (PMID 22238649, 2012). "Measuring the plasma somatostatin concentration by RIA, there was a reduced plasma somatostatin concentration between 8 and 64 weeks of infection in WT-infected gerbils (data not shown)." (PMID 19270747, 2009).
brain disorder (10 papers, 2012 to 2026). A disease affecting the brain or part of the brain. "The neuropeptide, somatostatin, has been linked to hormone release, cell proliferation, and many pathophysiological processes of brain disorders." (PMID 22701680, 2012). "Deficits in SST neurons in mammals have been linked to dysregulated attention, episodic memory, and spatial navigation and have been observed across multiple brain disorders as well as in healthy aging, suggesting SST cell-intrinsic vulnerability." (PMID 41159096, 2026). "Our results identify alterations in NAc induced by cocaine in a sparse population of somatostatin interneurons, and illustrate the value of studying brain diseases using cell type-specific whole transcriptome RNA-sequencing." (PMID 30089879, 2018). "Future studies will assess if lower SST expression in brain disorders affects a proportion of SST cells, similar to aging, or lower expression across cells." (PMID 29079825, 2017). "However, the attribution of SST in the control of various human brain diseases demands in-depth information, such as specific laminar distribution, distinct cell types, and specific cortical wiring patterns of SST neurons." (PMID 35052772, 2022). "Exploring cross-disease molecular (somatostatin) and cellular (somatostatin-expressing interneurons) pathological findings suggests a dimensional pathological phenotype that is specific to the somatostatin gene/cell biological entity rather than to categorical brain disorders." (PMID 24058344, 2013). "Subgenual anterior cingulate cortex (sgACC) of human subjects without brain disorders were labeled using fluorescent in situ hybridization (FISH) for CRH and markers of excitatory (SLC17A7), inhibitory (GAD1) neurons, as well as markers of other interneuron subpopulations (PVALB, SST, VIP)." (PMID 35280164, 2022).
neurodegenerative disease (10 papers, 2011 to 2025). A disorder of the central nervous system characterized by gradual and progressive loss of neural tissue and neurologic function. "The loss of PV-INs might also be an indirect consequence of the loss of other neurons and consequent innervation, including somatostatin-expressing interneurons also reported in 5xFAD mice, as recently proposed for neurodegenerative diseases." (PMID 41313510, 2025). "In several pathological conditions including neurodegenerative diseases and tumors of different origin, somatostatin (SST) via its five receptor subtypes plays crucial role and serves as an important therapeutic approach." (PMID 21838893, 2011). "To summarize, our findings suggest two independent mechanisms by which SST mediates neuroprotection and confirms the therapeutic implications of SST in AD as well as in other neurodegenerative diseases where the effective regulation of calcium homeostasis is required for a better prognosis." (PMID 33401710, 2021). "Targeting these pathways may exert neuro-protective effects on somatostatin-expressing neurons, as a potential therapeutic approach with implications for several neuropsychiatric disorders and neurodegenerative diseases." (PMID 24058344, 2013). "Taken together, our results indicate that SST and SSTRs might play an important neuroprotective role in neurodegenerative diseases." (PMID 21912697, 2011).
neurological disorders (10 papers, 2013 to 2025). "MGE-derived PV and SST-expressing interneurons have shown specific importance in the physiological signaling regulation, with their dysfunction linked to several neurological disorders." (PMID 40930061, 2025). "Accordingly, there are currently very few reports linking somatostatin gene polymorphisms with neurological disorders." (PMID 24058344, 2013). "Taken together, the results described here support the use of SH-SY5Y cells to delineate the role of SST in neuritogenesis with a possible implication in neurological diseases exhibiting interrupted neuronal communication, loss of cognitive function, and memory." (PMID 35203546, 2022). "Also, SST interneurons in the mPFC are known to play a role in working memory by regulating the excitation/inhibition balance, and dysregulation of SST interneurons is associated with neurological disorders such as schizophrenia." (PMID 40211051, 2025). "With this knowledge, links can be made between SST function and SST-related neurological disorders in humans." (PMID 35052772, 2022). "In striatum and cortical brain regions, bNOS and SST are co-expressed and selectively spared in excitotoxicity and neurological diseases." (PMID 35203546, 2022). "The evidence outlined in this review provides only a glimpse of the potential full range of somatostatin deficits across neurological disorders, as multiple other brain regions and disease categories await further characterization." (PMID 24058344, 2013). "As such, it is essential to identify upstream factors responsible for the dysfunction of somatostatin-expressing interneurons in neurological disorders." (PMID 24058344, 2013). "For example, are the prevalent somatostatin deficits seen in multiple diseases reflected in a common symptom dimension, such as low mood, across neurological diseases?" (PMID 24058344, 2013). "Finally, we discuss potential treatments and possibility of novel drug developments for neurological disorders based on the current knowledge on the function of SST and SST analogs in the brain derived from experimental and clinical studies." (PMID 33742131, 2021). "These canonical pathways might provide novel cell-based perspectives in the treatment of affected somatostatin-expressing cells across neurological disorders." (PMID 24058344, 2013). "Finally, the fact that somatostatin deficits are frequently observed across neurological disorders suggests a selective cellular vulnerability of somatostatin-expressing neurons." (PMID 24058344, 2013). "This channel predominates in a subpopulation of layer II/III somatostatin-(SST) containing neurons that always expresses reelin, a matrix extracellular protein which, in the adult cortex, play an important role in synaptic plasticity and in abundant neurological disorders." (PMID 29535613, 2018). "Hence, decreasing somatostatin expression due to cellular impairment in the progress of neurological diseases may further enhance inflammation in a vicious cycle, leading to exacerbated cellular vulnerability of somatostatin-expressing neurons." (PMID 24058344, 2013). "Hence, this review is not comprehensive, but rather, highlights the recent findings in brain somatostatin signaling and the potential role of somatostatin deficits in affect dysregulation for integrating categorical models of mood symptoms into a dimensional model across neurological disorders." (PMID 24058344, 2013). "Clarifying the role of somatostatin and its regulation of GABA inhibition in affect regulation could provide new strategies for predicting, delaying, and treating neurological diseases with mood disturbances." (PMID 24058344, 2013). "Taken together, the cumulative evidence demonstrates that somatostatin deficits are common neurochemical and molecular features in individuals with neurological disorders, regardless of their categorical diagnosis." (PMID 24058344, 2013).
neurological disorders (continued). "So far, these findings suggest that somatostatin deficits across different brain systems and diseases may play a central role in the affective symptom dimension rather than non-specific signals in neurological disorders." (PMID 24058344, 2013).
psychiatric disorder (10 papers, 2018 to 2025). A disorder characterized by behavioral and/or psychological abnormalities, often accompanied by physical symptoms. "Clinical and preclinical studies have identified somatostatin (SST)-positive interneurons as key elements that regulate the vulnerability to stress-related psychiatric disorders." (PMID 39041032, 2024). "The products of SST and NPY, somatostatin and neuropeptide Y, respectively, often serve as important biomarkers in psychiatric disorders." (PMID 29958387, 2018). "However, no drugs targeting the SST system are approved or under investigation in clinical trials for the treatment of neurodegenerative and psychiatric disorders, mainly because current SST analogs cannot penetrate the blood–brain barrier." (PMID 35800635, 2022). "However, somatostatin-expressing (SST+) and vasoactive peptide-expressing (VIP+) interneurons contribute substantially to regulating GABAergic inhibition in the cortex and dysfunction of these interneurons are associated with psychiatric disorders." (PMID 35185505, 2022). "By engineering exosomes to display SST or CCK, researchers aim to improve targeting specificity toward cells expressing SST or CCK receptors, such as neurons or glial cells involved in neurodegenerative or psychiatric diseases." (PMID 40533746, 2025). "Mounting evidence implicates the dysfunction of GABAergic signaling in the etiology of psychiatric disorders, including addiction, PTSD, and MDD, where reduced SST expression in the human amygdala has been observed in postmortem tissue." (PMID 40961182, 2025).
neurodevelopmental disorder (4 papers, 2015 to 2023). A behavioral and cognitive disorder with onset during the developmental period that involves impaired or aberrant development of intellectual, motor, or social functions. "This dataset will be useful in future studies of SST+ development and as a comparison to SST+ distribution in neurodevelopmental disorder models with a suspected impact on SST+ neurons." (PMID 37222748, 2022).
gastrointestinal tumors (3 papers, 2015 to 2022). "In the future, an in-depth functional study of SST-specific CpG sites is expected to reveal the molecular mechanism of abnormal SST methylation involved in the development of gastrointestinal tumors." (PMID 35242243, 2022). "SST promoter hypermethylation was revealed in several gastrointestinal tumors in the past decade." (PMID 25723531, 2015). "It is interesting to note that gastrointestinal tumors exhibit a high expression of SST receptors, a fact that might represent a feedback mechanism following the decreased expression of somatostatin." (PMID 32243066, 2020).
endocrine tumor (2 papers, 2021). "Determination of serum SST levels as a potential marker of endocrine tumor differentiation (including CRC) does not provide conclusive results." (PMID 34829972, 2021).
inflammation (1 paper, 2011). Aberrant reaction of the microcirculation characterized by movement of fluid and leukocytes from the blood into extravascular tissues. "Proteomic analysis with agarose 2D electrophoresis shows expression of spectrin α2, a high molecular weight protein (∼240 kDa), was down-regulated in the lung tissue of airway inflammation model mouse, and the expression was recovered by administration of SST." (PMID 19861507, 2011).
SST also shares sentences with these, for which no sentence is quoted: adenocarcinoma (4 papers); Dravet syndrome (4); gastrinoma (4); pheochromocytoma (4); autosomal dominant polycystic kidney disease (3); esophageal adenocarcinoma (3); head and neck cancer (3); somatotroph adenomas (3); anorexia nervosa (2); carcinoid tumours (2); chronic gastritis (2); duodenal ulcer (2); endometriosis (2); H. pylori (2); heart failure (2); hepatorenal syndrome (2); hypothyroidism (2); kidney disease (2); Liver cirrhosis (2); lupus erythematosus (2); medulloblastoma (2); metabolic disease (2); multiple sclerosis (2); nasopharyngeal carcinoma (2); pancreatic ductal adenocarcinoma (2); Parkinson (2); renal cell carcinoma (2); ulcerative colitis (2); Zollinger-Ellison syndrome (2); acquired immunodeficiency syndrome (1).
A further 95 diseases each share a sentence with SST in 1 paper.